INS (insulin)
Diseases named in the same sentence as INS in open-access papers (continued):
Sharing a sentence is not in itself a finding about the gene and the disease.
hyperuricemia (142 papers, 2004 to 2026). An abnormally high level of uric acid. "A population study of 14 664 Americans demonstrated that higher insulin levels were associated with hyperuricemia." (PMID 39560012, 2025). "IR and SU levels were described bidirectionally interconnected because higher SU levels are known to adversely affect the insulin signaling pathway causing IR while IR is a known predictor for the development of hyperuricemia." (PMID 40607233, 2025). "We found that four non-insulin-based indexes of IR were significantly associated with the risk of hyperuricemia." (PMID 38172828, 2024). "By improving insulin sensitivity, antioxidants help maintain normal uric acid metabolism and reduce the risk of hyperuricemia." (PMID 38966221, 2024). "In another study by Liu and his colleagues, the associations between hyperuricemia and three non-insulin-based IR indexes, including TG/HDLc, TyG, and METS-IR, were investigated." (PMID 38172828, 2024). "The association between hyperuricemia and non-insulin-based indexes of IR has been assessed in a limited number studies that have been inconsistent in their results." (PMID 38172828, 2024). "In our study, increasing the score of all non-insulin-based indexes of IR was associated with an increase in the risk of hyperuricemia." (PMID 38172828, 2024). "China leads TyG index research, with a focus on its association with insulin sensitivity, BMI, and hyperuricemia." (PMID 39465764, 2024). "In this national cohort study, positive associations were identified between four non-insulin-based IR indicators and risk of hyperuricemia among middle-aged and older Chinese individuals." (PMID 37513557, 2023). "Gout is caused by long-standing hyperuricemia, and although fasting insulin can genetically elevate in serum urate, the concentration or duration of the elevated serum urate is not sufficient to cause gout." (PMID 35992130, 2022). "Hyperuricemia has been associated with reduced insulin sensitivity, as demonstrated in Facchini's study." (PMID 32118009, 2020). "Hyperuricemia is probably associated with glucose intolerance due to various mechanisms; however, the most important is the association between insulin and renal resistance to absorption of urates." (PMID 22216028, 2011). "Moreover, insulin resistant adipose tissue has been independently linked to a higher risk of developing hyperuricemia." (PMID 40943711, 2025). "However, few studies have investigated the association between non-insulin-based indexes and hyperuricemia." (PMID 38172828, 2024). "As mentioned, UA stone formation might be attributed to aciduria, hyperuricosuria, or hyperuricemia, which could be caused by insulin resistance, altered purine metabolism, or impaired renal function." (PMID 38898140, 2024). "These nutrient-specific mechanisms may include the unregulated hepatic fructose metabolism that causes hepatic lipid accumulation, hyperuricemia and decreased insulin sensitivity, and hence MetS." (PMID 35139893, 2022). "A previous study suggested that hyperuricemia may cause inflammatory responses in adipose tissues causing increased inflammation and insulin resistance and promote fat storage." (PMID 36590930, 2022). "Second, the resorption of sodium and uric acid in the proximal tubule may be increased by insulin and cause hyperuricemia." (PMID 32182733, 2020). "Furthermore, stratified analyses indicated that maintaining high levels of four insulin surrogates significantly increased the risk of hyperuricemia in both genders compared to maintaining low pattern (all p < 0.05), with higher adjusted ORs for females than males." (PMID 37513557, 2023). "Hormonal disruptions, including changes in insulin sensitivity, also purine metabolism, leading to hyperuricemia and further complications in kidney health and gout." (PMID 40273216, 2025). "In turn, high insulin levels resulting from insulin resistance suppress renal uric acid secretion and increase UA-producing substrates, leading to hyperuricemia." (PMID 40486823, 2025).
hyperuricemia (continued). "In adolescents, insulin, fasting glucose, blood pressure and %BF values have been significantly higher in those with hyperuricemia." (PMID 40717997, 2025). "Temporary hyperuricemia induced by exhaustive RE and fructose intake appeared to have marginal effects on insulin sensitivity and secretion, as demonstrated by the derived HOMA-IR and HOMA-β values in the participants." (PMID 40410816, 2025). "He continued oral prednisolone 12.5 mg daily and had linagliptin 5 mg, insulin degludec once daily, and insulin lispro before each meal for corticosteroid-induced diabetes mellitus, and febuxostat 10 mg for hyperuricemia." (PMID 40385891, 2025). "In our future research, we will further conduct studies on the correlation between hyperuricemia and blood glucose and insulin." (PMID 40808845, 2025). "Metformin also promoted the phosphorylation of AMP-activated protein kinase (AMPK) and restored insulin-stimulated glucose uptake in hyperuricemia-induced IR cardiomyocytes." (PMID 38579756, 2024). "The study pinpointed the V-type proton ATPase subunit B kidney isoform and Complex Factor D (CFAD or adipsin) as key factors impacting insulin regulation in hyperuricemia patients." (PMID 39191722, 2024). "In the context of hyperuricemia, elevated levels of uric acid significantly disrupt insulin signaling pathways, thereby diminishing insulin-induced eNOS activation and expression as well as NO synthesis in endothelial cells." (PMID 38548844, 2024). "In both Beijing and Taiyuan, the median HbA1c, SBP, hyperuricemia, and insulin usage (both current and follow-up medication) in group 1 were significantly higher than in group 2 (P < 0.001)." (PMID 37408009, 2023). "One important mechanism has been suggested that hyperuricemia impairs insulin-mediated glucose uptake in skeletal muscle by reducing blood flow and the release of nitric oxide release from endothelial cells." (PMID 38169712, 2023). "Hyperuricemia is thought to result from decreased insulin‐dependent renal tubular uric acid excretion and/or increased fructose‐dependent uric acid production." (PMID 36415168, 2023). "Even after adjusting for insulin level plus FBG, or HOMA-IR, RBP4 remained strongly associated with hyperuricemia." (PMID 35846279, 2022). "This study showed that hyperuricemia-induced circulating monocytes were recruited into the mouse liver; these macrophages exhibited impaired glucose uptake, insulin sensitivity, and insulin signaling pathways." (PMID 36177037, 2022). "Some animal studies have reported that hyperuricemia can reduce insulin sensitivity by increasing reactive oxidative stress and inflammatory cytokines such as TNF-alpha." (PMID 35740443, 2022). "As a result of these effects, in a mouse model of acute hyperuricaemia, metformin improved insulin tolerance and glucose tolerance, accompanied by increased AMPK phosphorylation, Akt phosphorylation and translocation of GLUT4 in myocardial tissues." (PMID 34053175, 2021). "Kumric, in a recent review concerning HF and SUA, has identified two main mechanisms of hyperuricemia in this patient population: the hypoxia typical of progressive HF, catabolism, and cell apoptosis, and frequent insulin resistance stimulate XO activities." (PMID 33922386, 2021). "Our acute hyperuricaemia mouse model also indicated an impaired glucose tolerance test and insulin tolerance test at 15 and 30 minutes after insulin or glucose injection with insulin resistance." (PMID 34053175, 2021). "In short-term feeding trials and experimental studies, high-fructose intake resulted in hyperuricemia and incident gout and increased insulin resistance." (PMID 33653403, 2021). "Our meta-analysis of RCTs provided the evidence that uric acid-lowering in hyperuricemia patients significantly improved insulin sensitivity and lowered BP." (PMID 34394285, 2021).
hyperuricemia (continued). "Second, hyperuricemia can increase reactive oxygen species production and inhibit insulin-induced glucose uptake by increasing the phosphorylation of insulin receptor substrate 1 and inhibiting the phosphorylation of Akt." (PMID 34335617, 2021). "Our incidence of preoperative hyperuricemia decreased from 66.7 to 33.3% postoperatively, possibly due to enhanced insulin sensitivity after LSG." (PMID 28822064, 2018). "Comparative analysis of biochemical variables between hyperuricemia group and controlgroup showed similar serum levels of glucose, insulin, HOMA-IR, total cholesterol,LDL-cholesterol, TG and hs-CRP." (PMID 30328946, 2018). "Hyperuricemia is a frequent finding in insulin-resistant states and plays an important role in dysregulation of glucose uptake." (PMID 30425752, 2018). "Further, too much insulin action can reduce excretion of uric acid in the renal tubules, which in turn leads to hyperuricemia." (PMID 29109738, 2017). "Insulin acts on the proximal renal tubule fostering acid uric reabsorption and increasing renal cellular metabolism, thus leading to hyperuricemia." (PMID 27077854, 2016). "Phospho-Akt level was lower in cardiac tissues of acute hyperuricemic mice than controls, with no change in IR, which demonstrates a profound effect of hyperuricemia on downstream insulin signaling in vivo." (PMID 26836389, 2016). "The reasoning for these recommendations relates to the well-described weight gain with beta-blockers and the adverse metabolic effects (such as insulin resistance and hyperuricemia) encountered with both beta-blockers and diuretics." (PMID 23533713, 2013). "Furthermore, visceral fat area, but not subcutaneous fat area, is associated with a decrease in peripheral insulin sensitivity in type 2 DM, which may decrease the urinary excretion of uric acid and this may causes hyperuricemia especially in the subjects with type 2 DM." (PMID 22301198, 2012). "In a study that reported beta cell function with HOMA in subjects with hyperuricemia, failure of beta cells to compensate for the variation in insulin sensitivity was demonstrated." (PMID 22216028, 2011). "Insulin secretion was stimulated with L-arginine, and it was observed that in subjects with hyperuricemia and insulin resistance beta cell function increased from its compensatory state." (PMID 22216028, 2011). "Serum concentration of uric acid showed a positive relationship with the total phase of insulin secretion; even in states prior to hyperuricemia, uric acid can play an important role in the function of the beta cell in patients with DM2." (PMID 22216028, 2011). "The interplay between insulin physiology and hyperuricemia might also explain why women with gout in our study had a higher likelihood of experiencing GDM compared to women without gout." (PMID 39560012, 2025). "It is known that hyperuricemia might be contributed to the effect of insulin on decreasing renal urate clearance and sodium excretion in individuals." (PMID 38347000, 2024). "The simultaneous impact of low insulin release, consuming low glycemic index foods and increased ketone bodies might contribute to the observed transient pattern of hyperuricemia in KD." (PMID 37380733, 2023). "In addition to glycemic control, dapagliflozin shows the favourable influence on body weight, blood pressure, insulin resistance, silent inflammation, oxidative stress and hyperuricemia." (PMID 38223613, 2023). "The effects of IR on incident hyperuricemia may vary across gender, possibly because females have distinct sex hormones and adipokines that make them more responsive to insulin than male." (PMID 37513557, 2023). "The amelioration of IR decreased the serum UA level independent of weight loss, while the UA-lowering therapy did not change insulin sensitivity in hyperuricemia subjects." (PMID 35757425, 2022).
hyperuricemia (continued). "Possible mechanism may be that hyperuricemia induces oxidative stress by increasing reactive oxygen species (ROS) level, which interferes the insulin signaling pathway." (PMID 36064644, 2022). "Decreased GSIS in hyperuricemia may be due to decreases in MafA protein expression as MafA is a key regulator of insulin secretion in β-cells." (PMID 33593356, 2021). "The mechanism may be that hyperuricemia increases phospho-IR substrate 1 (Ser307) and inhibits phospho-protein kinase B (Akt) response to insulin in myocardial tissues." (PMID 34867815, 2021). "Because NCXmito is involved in insulin secretion from β-cells, one can speculate that hyperuricemia can affect β-cell function via this pathway." (PMID 33593356, 2021). "Notably, hyperuricemic mice develop insulin resistance and suffer from impaired glucose tolerance suggesting possible inhibition of insulin signaling in hyperuricemia." (PMID 34408667, 2021). "Li Zhi et.al reported hyperuricemia could increase ROS production and inhibit insulin-induced glucose uptake in H9c2 and primary cardiomyocytes." (PMID 34867815, 2021). "The hyperuricemia‐induced oxidative stress could inhibit insulin signaling through the phosphorylation of Akt and insulin receptor substrate‐1 (IRS‐1), and/or lowering phospho‐Akt content in the adipose tissue without changes in total Akt." (PMID 31782919, 2019). "Therefore, in subjects with an eGFR > 1 SD or hyperuricemia, we encourage to investigate the early-phase insulin secretion and 2-hour post-challenge glucose levels." (PMID 29505614, 2018). "Therefore, pediatric obese patients with eGFR > 1 SD or hyperuricemia should be closely monitored for microalbuminuria and post-challenge glucose and insulin secretion, all potential indicators of renal dysfunction in these young patients." (PMID 29505614, 2018). "In particular, hyperuricemia inhibited a protein kinase B (AKT) response to insulin by decreasing its phosphorylation and conversely increasing the phosphorylation of the insulin receptor substrate-1 (IRS1) in liver, muscle and fat tissue, thus fostering the onset of IR." (PMID 27077854, 2016). "One possible biological mechanism is related to insulin-stimulated endothelial nitric oxide synthesis, and hyperuricemia may induce endothelial cell dysfunction and contribute to the development of MetS." (PMID 25136366, 2014). "Hyperuricemia, characterized by elevated serum uric acid levels, has been increasingly recognized as a potential risk factor for the development of T2DM, underscoring the need for a deeper understanding of its pathophysiological impact on glucose metabolism and insulin sensitivity." (PMID 41019336, 2025). "In addition to insulin, lipids also play a significant role in the pathogenesis of hyperuricemia." (PMID 38933825, 2024). "Additionally, the ROS formation escalation following hyperuricemia could result in a decrease in the transcription factors necessary for the expression of the insulin gene, and a reduction in insulin synthesis and release." (PMID 37671195, 2023). "Besides, since fasting serum insulin levels were significantly higher in both premenopausal and postmenopausal women with hyperuricemia than in men with hyperuricemia, sex hormones may also play a role." (PMID 32733967, 2020). "In addition, in an experimental model, mice fed with hyperuricemia-inducing diet (HUA) presented significantly lower insulin sensitivity and impaired glucose metabolism compared to those with a standard diet, as well as higher levels of both serum and intrahepatic triglycerides." (PMID 27077854, 2016). "Insulin-resistant Otsuka Long–Evans Tokushima Fatty (OLETF) rats and the control, Long–Evans Tokushima Ohtsuka (LETO) rats, were used as a model for acute hyperuricemia." (PMID 38474414, 2024).
hyperuricemia (continued). "The optimum model for predicting hyperuricemia in the general population consisted of RBP4, sex (male), body mass index, serum creatinine, high-sensitivity C-reactive protein, fasting blood glucose, insulin, and alcohol consumption." (PMID 35846279, 2022). "The aim of this study was to determine the relationship between serum concentrations of uric acid with insulin secretion in adults with DM2 without hyperuricemia using the hyperglycaemic clamp technique." (PMID 22216028, 2011). "The role of uric acid as a continuous variable and its relationship to insulin secretion without hyperuricemia in patients with DM2 in a model such as the clamp has not been evaluated." (PMID 22216028, 2011). "In the present study, we found that the diet-induced hyperuricemia mouse model revealed an increasing apoptosis of pancreatic β cells using TNUEL, which targets the core markers of apoptosis (DNA damage), ultimately decreasing β cell mass and insulin secretion with the progress of hyperuricemia." (PMID 40710003, 2025). "In addition, there were higher values of SBP, DBP, WC, BMI, TG, LDL, FBG, insulin, HOMA-IR, SCr, cystatin C, NAG, hs-CRP, IL-6, and RBP4 in the hyperuricemia group compared to the non-hyperuricemia group (P<0.05), but lower values of HDL, eGFR, and serum uric acid (P<0.001)." (PMID 35846279, 2022). "Insulin may enhance renal urate reabsorption through the stimulation of the urate-anion exchanger URAT1 in the brush border membranes of the renal proximal tubules, which can lead to hyperuricemia." (PMID 35055342, 2022). "In addition, a positive correlation between serum UA and total insulin secretion has been reported using a hyperglycemic clamp technique in type 2 diabetic patients without hyperuricemia." (PMID 33593356, 2021). "The median age, BMI, waist circumference, insulin levels, HOMA, systolic and diastolic blood pressures, serum concentrations of lipids, fasting glucose, creatinine, and uric acid levels were greater among patients with hyperuricemia, compared to the controls in the different cohorts." (PMID 31207883, 2019). "However, there are no previous studies showing the possible relationship of serum uric acid with different phases of insulin secretion using a hyperglycemic-hyperinsulinemic clamp technique in subjects with DM2 without hyperuricemia." (PMID 22216028, 2011). "Children with hyperuricemia had lower peak stimulated GH and HDL-C, and higher values for HOMA-IR, insulin, TG, ALT than subjects with no hyperuricemia." (PMID 29785038, 2018). "Compared with women with PCOS without hyperuricemia, women with PCOS with hyperuricemia had significantly greater BMI, NC, WC, HC, SBP, DBP, fasting insulin, HOMA-IR, HOMA-β, TC, TG, LDL, basal T and serum uric acid levels, while the basal FSH and HDL levels were lower (all P<0.05)." (PMID 34552558, 2021).